STAT3 (signal transducer and activator of transcription 3)
Diseases named in the same sentence as STAT3 in open-access papers (continued):
Sharing a sentence is not in itself a finding about the gene and the disease.
tumor (continued). "Either or both molecular mechanisms could result in one or more downstream anti-cancer effects such as increased tumor cell apoptosis, inhibiting Hedgehog or growth factor signaling between PDAC and PSC cells, and/or suppressing effectors of the RAS, PI3K/Akt or JAK/STAT3 pathways." (PMID 34262644, 2021). "In other studies, ginsenoside Rg3 has been shown to inhibit angiogenesis in a variety of tumor models and was shown to inhibit hypoxia-induced VEGF expression in tumor cells through regulation of various pathways, such as Akt, ERK, JNK, and STAT3 signaling pathways." (PMID 35002732, 2021). "In addition to their well described role in immunosuppression, MDSC have also been shown to confer stem-like phenotypes to tumor cells through various mechanisms including MDSC secretion of IL-6, activation of STAT3 or induction of miRNA expression in tumor cells." (PMID 33805598, 2021). "Importantly, similar to short-term Olaparib treatment, RT-PCR analysis of parental and Olaparib-resistant A2780, OVCAR8, and PEO1 cells showed mRNA upregulation of several essential tumor-promoting genes, such as MMP9, VEGFA, CCND1, and BCL2L1, which are known STAT3 target genes." (PMID 34956861, 2021). "Furthermore, Ob-R can upregulate downstream the JAK/STAT3, PI3/AKT, and RhoA/ROCK signaling pathways, ultimately leading to the promotion of the epithelial-mesenchymal transition (EMT) and contributing to the maintenance of a staminal phenotype in tumor cells." (PMID 34440886, 2021). "At the same time, inhibition of miR-216a-5p or IL-6 induced cells after tumor cell stemness transformation is promoted, and the effect of LNT is reversed, indicating that LNT is involved in cell stemming by regulating miR-216a-5p targeting and mediating the JAK2/STAT3 signaling pathway." (PMID 34900727, 2021). "However, when Lgp130 was expressed in hepatocytes, we did not observe tumour formation in aged mice, despite persistent gp130/STAT3 activation." (PMID 34047814, 2021). "Previously, and in order to establish the role of STAT3 in the ccRCC, our group analyzed the expression of both phosphorylated residues (pY705 and pS727) on localized tumor samples from 98 ccRCC patients who had not undergone chemo- or immunotherapy before or after nephrectomy." (PMID 33772065, 2021). "Moreover, in orthotopic implantation xenograft tumor of MHCC97-L, HMH-exosomes (HCC-LM3 exosomes and MHCC97-H exosomes) significantly enhanced nuclear STAT3 phosphorylation and cytoplasmic OPN expression while LMH exosomes (HepG2 exosomes) or PBS could not." (PMID 34035222, 2021). "Interestingly, more recently, concomitant absence of STAT1 and STAT3 was reported in CRC tumor tissue, which was found to be significantly correlated with shorter overall survival of CRC patients." (PMID 33846436, 2021). "The tumor-intrinsic immunosuppression usually involves the activation of various oncogenic pathways, including Wnt–β-catenin, mitogen-activated protein kinase (MAPK), Janus kinase (JAK)–signal transducer and activator of transcription 3 (STAT3) and nuclear factor-κB (NF-κB) signaling pathways." (PMID 34774008, 2021). "Finally, STAT3 elicits the release of the pro-inflammatory proteins S100A8/A9, which inhibit dendritic cell (DC) differentiation, ultimately favouring MDSC migration and accumulation within the tumour site." (PMID 34685679, 2021). "Moreover, STAT3 signaling was proved to inhibit the expression of activation receptor NKD2G on NKs and its corresponding ligands MICA/B on tumor cells, which could block the activation of NKs and result in failing immune surveillance in HCC." (PMID 34566989, 2021). "Several other tyrosine kinase inhibitors (TKI) also induce CTL-driven anti-tumor immune responses, including sunitinib, a broad spectrum RTK inhibitor that targets VEGFR, PDGFRα, Ret, and Kit, which has been shown to reverse immune suppression by inhibiting STAT3 signaling in renal cell carcinoma." (PMID 33807608, 2021).
tumor (continued). "Moreover, DHA impacts STAT3-induced EMT and MMPS in tumor tissue." (PMID 34539408, 2021). "Results from chromatin immunoprecipitation (ChIP) assays showed increased binding of p65 and cJun but not (p)STAT3 on the promoter of Il1f9 gene in the tumor tissues compared with the normal lung tissues from KrasLSL‐G12D/+Lkb1fl/fl mice that were intranasally injected with Ad‐Cre or Ad‐Vec." (PMID 34369094, 2021). "Janus kinase-signal transducer and activator of transcription 3 (STAT3) inhibition: In KRAS-mutant NSCLC, after inhibiting MEK, STAT3 is activated via fibroblast growth factor receptor and Janus kinase; combined inhibition of this receptor, MEK, and Janus kinase can promote tumour regression." (PMID 34012925, 2021). "Taking together, these results not only pointed out the potential roles of aberrant CDK2/4/6 expression in the initiation and development of multiple cancer but also suggest that STAT3 and CDK2/4/6 expression may alter tumor immune microenvironment and hence involved in cancer immune responses." (PMID 33668805, 2021). "The deletion of the Stat3 gene increased the level of two cytolytic enzymes perforin and granzyme B in mouse NK cells and accordingly a lack of STAT3 signaling enhanced the NK cell-dependent tumor surveillance." (PMID 34476533, 2021). "Besides, FAK/PI3K/AKT/STAT3/NF-κB and nSMase2/MAPK/NF-κB pathways may be novel targets for regulating tumor growth and metastasis in ESCC patients." (PMID 34844621, 2021). "As AKT and STAT3 pathways were proven to be important for PC tumorigenesis, it would be reasonable to propose that CXCL5/CXCR2 signaling might activate AKT and STAT3 signaling pathways to promote tumor progression in PC." (PMID 33458757, 2021). "The JAK2/STAT3 pathway participates in cancer cell survival, proliferation and progression by regulating multiple processes, such as epithelial–mesenchymal transition (EMT), which is required for tumor metastasis, and molecular signals that control other cancer hallmarks." (PMID 33805840, 2021). "Moreover, it is indicated that STAT3 phosphorylation is involved in EMT and tumor metastasis." (PMID 34789307, 2021). "Finally, it appears important to underline the cooperative action of IL-6, IL-10, and TGF-β in determining higher STAT3 activity and thus STAT3-mediated negative effects on the immune responses in the tumor stroma." (PMID 33806300, 2021). "Interestingly, transcriptome pathway enrichment analysis demonstrates that MGF inhibits tumor growth, metastasis and angiogenesis by multi-targeting of mitochondrial oxidoreductase and fatty acid β-oxidation metabolism, PPAR, SIRT, NFκB, Stat3, HIF, Wnt and GP6 signaling pathways." (PMID 34924998, 2021). "Some studies have also shown, that IL6 signaling can lead to STAT3 activation, further by promoting expression of vascular endothelial growth factor (VEGF) and fibroblast growth factor (bFGF) by tumor cells, supporting the rapid vascularization within tumor tissues." (PMID 34445494, 2021). "While epithelial ablation of STAT3 did not impact the initial hyperplastic expansion of the epithelial tree, the nascent lesions were eliminated by massive immune response involving both anti-tumor macrophage and T cell populations." (PMID 33235291, 2021). "Anti-tumor effects could be increased by combining the PD-1/PD-L1 blockade with other approaches (inhibitors of tyrosine kinase, PI3K/mTOR or JAK/STAT3 pathways, p300/CBP; anti-RANKL and/or anti-CTLA-4 antibodies; cytokines; nitroxoline; DNA/cell vaccines; radiotherapy/Radium-223)." (PMID 34830179, 2021).
tumor (continued). "Anti-tumor effects could be increased by combining PD-1/PD-L1 blockade with other approaches (inhibitors of tyrosine kinase, PI3K/mTOR or JAK/STAT3 pathways, p300/CBP; anti-RANKL and/or anti-CTLA-4 antibodies; cytokines; nitroxoline; DNA/cell vaccines; radiotherapy/Radium-223)." (PMID 34830179, 2021). "Furthermore, in HCC tumor cells, icaritin did not affect the expression of STAT3, known to be required for cytotoxicity induced by icaritin." (PMID 33717093, 2021). "In addition, imatinib single treatment showed no inhibitory effects on the expression of p-STAT3 in tumour tissues." (PMID 34214017, 2021). "Therefore, our results indicated that apatinib might exert its inhibitory effects on NSCLC by targeting VEGFR2/STAT3/PD-L1 signaling in both NSCLC cells and tumor derived macrophages and partially restoring theactivation of T cells." (PMID 34429133, 2021). "Additionally, STAT3 is a key inducer of immune suppressive cytokines (IL-10, IL-4, IL-6 and TGF-β), maintains immunosuppressive cell cross-talk, increases tumor infiltration by MDSCs, and induces T cell arrest and apoptosis." (PMID 34440802, 2021). "In vivo and in vitro experimental results suggested that the YPF formula could downregulate the expression levels of MDSCs proliferation-related proteins including phospho-STAT3, phospho-Akt, phospho-MEK, and phospho-ERK, thus leading to a marked decrease of MDSCs in the tumor microenvironment." (PMID 33986819, 2021). "Our study identifies MARCH8 as a new tumor suppressor in inhibiting breast cancer metastasis and enhancing cancer cell death, partially via the lysosomal degradation of the breast cancer stem-cell marker CD44, as well as via the proteosome-dependent degradation of STAT3." (PMID 34067416, 2021). "Despite this evidence, the inhibition of STAT3 may not be sufficient to completely eliminate the tumor following radiation treatment." (PMID 34141616, 2021). "In addition, blocking CME in the refractory cell lines led to downregulate of p‐STAT3 and inhibit nuclear localization of STAT3 in vivo, combination treatment with gefitinib and a CME inhibitor resulted in tumor regression accompanying apoptosis in xenograft mouse models." (PMID 33314735, 2021). "Interestingly, the STAT3 tumors that escaped immune surveillance failed to metastasize to distal organs, indicating that STAT3 was critical for the metastatic phase of tumor induction." (PMID 33235291, 2021). "Last but not least, STAT3 expression enhances tumor angiogenesis." (PMID 33672684, 2021). "In addition, the anti-tumor effects of JAK2/3 inhibitor AG490 was observed in WT mice but not in Rab37 KO mice, consistent with the hypothesis of Rab37/IL-6/STAT3/PD-1 functioning in the same axis." (PMID 34093869, 2021). "In addition to STAT3, these included SMARCA2, a tumor suppressor involved in various cancers, SOCS1, a STAT-inhibitor, DNMT3A, with known somatic mutations in the context of clonal hematopoiesis and PPP3CA encoding calcineurin-A, involved in T-cell receptor signaling." (PMID 34874980, 2021). "In the same model, an ATX-enriched diet (15 mg/kg) suppressed tumor progression via inhibition of the JAK/STAT3 signaling pathway and its downstream targets cyclin D1, MMP-2 and -9, and VEGF, preventing cell proliferation and invasion and, consequently, regulating tumor microvascular density." (PMID 34677429, 2021). "Also, tumour-derived exosomes can regulate monocytes via CD44H, a transmembrane protein on monocytes, that initiates phagocytosis and chemokine production, namely CCL5 and CCL4, via STAT3-mediated signalling." (PMID 34671031, 2021). "Consequently, the expression of GM-CSF, TSLP, phosphorylated STAT3, β-catenin, and cyclin D1 in the transplanted tumors was evaluated using Western blotting, and the expression of GM-CSF, TSLP, β-catenin and cyclin D1 was examined in tumor sections." (PMID 32887217, 2020).
tumor (continued). "Studies have found significantly increased tumor blood vessel formation in stressed animals, and the mechanism maybe a βARs-cAMP-PKA-IL-6-dependent activation of signal transduction and activator of transcription (STAT3)." (PMID 32974180, 2020). "IL-6 plays a critical role in the expansion and differentiation of tumor cells and can also modulate the tumor’s therapeutic resistance, such as multidrug resistance (MDR), whose engagement triggers the activation of JAK and the downstream effectors STAT3, SHP-2/Ras, and PI3K/Akt." (PMID 32847008, 2020). "Although EHD can regulate the STAT3/cyclin D1 pathway and delay the growth of LC, it could not completely inhibit the growth of xenograft tumours." (PMID 32382281, 2020). "Moreover, T cells, DCs and natural killer (NK) cells are immune cells that are directly involved in anti-tumor responses regardless of the tumor’s sensitivity to the STAT3 inhibitor." (PMID 32872659, 2020). "In addition, microRNA-19-a-3p inhibits tumor progression by downregulation of human fos-related antigen 1 (FRA-1) gene (acting as a pro-oncogene by supporting the invasion and progression of breast tumors) and the FRA/STAT3 signaling pathway in RAW264.7 cells." (PMID 32486098, 2020). "Since IL-6/STAT3/IL-10/TGF-β plays pivotal role in carcinogenesis and EMT39–43,45–48, to verify whether this axis is involved in malignant transformation of tumor cells regulated by transformed macrophage-CMs, we detected the changes of several major indicators in this process." (PMID 33288772, 2020). "Molecular mechanisms are not completely studied, but STAT3 activation by hypoxia-induced autophagy in tumor cells could, in theory, help in escaping CTL-mediated elimination, since this transcription factor controls the expression of anti-apoptotic genes." (PMID 33117715, 2020). "Therefore, it is not surprising that STAT3 signaling pathway has long been recognized as a potential therapeutic target for cancer therapy owing to their roles in tumor formation, metastasis and drug resistance." (PMID 32972405, 2020). "Finally, the tumor suppressor activity of P21 can be promoted by interaction with tumor-related factors like MYC, proliferating cell nuclear antigen (PCNA), and signal transducer and activator of transcription (STAT3)." (PMID 31998417, 2020). "Interestingly, in the cancer microenvironment a STAT3 activation loop between tumor cells and non-transformed cells including immune cells can be established." (PMID 33584695, 2020). "Our experimental results demonstrated that the Stat3 inhibitor BBI608 not only inhibited cell proliferation, colony‐forming ability, cell invasion and cell migration as well as increased cell apoptosis in vitro but also significantly enhanced the anti‐tumour effect of paclitaxel." (PMID 31778258, 2020). "Moreover, we discuss cutting-edge data on the link between EMT and CSCs in the tumor microenvironment that involves a previously unknown function of miRNAs, and also discuss new regulators of the JAK/STAT3 signaling pathway." (PMID 31952344, 2020). "Indeed STAT3 is involved in the differentiation and function of many other cell types, including TH17 cells that can be protective or deleterious in cancer, depending on the tumor type." (PMID 33143070, 2020). "Consistent with the in vitro results, caffeine significantly inhibited G6PDH enzymatic activity, p-STAT3 signaling activation, and cyclin E, NOX4, and p47-phox (NOX2 regulatory subunit) protein expression, and upregulated the expression of SOD2 protein, in xenografted RCC tumor tissues." (PMID 33123534, 2020). "Furthermore, the anti-tumor activities of type I IFNs can be limited by the activation of several survival pathways, such as the induction of the JAK2/STAT-3 pathway, the activation of nuclear factor kappa-beta (NF-κB) and the increased expression of the epidermal growth factor receptor (EGF-R)." (PMID 32967656, 2020).
tumor (continued). "The incorporation of the tumor-targeting, tissue-penetrating peptide, iRGD, results in an ability of the SPNPs to penetrate the highly selective BBB and distribute throughout the tumor volume, efficiently delivering siRNA against STAT3 without the use of invasive surgical procedures." (PMID 33173024, 2020). "Upon histological evaluation, the tumor population and the levels of active STAT3, Ki-67, Bcl-xL, and pro-MMP-2 were elevated, and that of active caspase-3 was decreased in vehicle-treated control mice, indicating that the proliferation and growth of tumor cells were active in this group." (PMID 32183406, 2020). "Stat3 is one of the Stats (Signal Transducers and Activators of Transcription) which are transcription factors that are phosphorylated by JAK kinases then dimerize and move into the nucleus and mainly activate the transcription of cytokine-responsive genes to initiate tumor growth and progression." (PMID 32754442, 2020). "The same microRNAs may even play different roles in different tumor subtypes: miR-410-3p significantly upregulates proliferation, invasiveness, cyclin B1 levels and activation of MAPK, PTEN/AKT, and STAT3 signaling pathways in gonadotroph and corticotroph cells but not in somatotroph cells." (PMID 32201880, 2020). "Persistent STAT3 activation in tumor cells results in increased cell proliferation, survival, and invasion; and at the same time, STAT3 exerts non-cell autonomous effects in the tumor microenvironment by boosting tumor-promoting inflammation and suppressing anti-tumor immunity." (PMID 32083000, 2020). "Tumor-derived microvesicles obtained from colorectal cancer cells promote the differentiation of blood monocytes into macrophages with mixed features of M1/M2 polarization, induce phosphorylation of STAT1 and STAT3 and change the secretion of cytokines such as IL-10, IL-12 and TNF." (PMID 32488850, 2020). "Consistent with the in vitro results, mice injected with ESM-1-overexpressing 4T1 cells exhibited significant increases in tumor volume, lung metastasis, metastasis-related molecules (VEGF, MMP-9, ICAM-1, and VCAM-1), and transcription factors (HIF-1α, phospho-NF-κB, and phospho-STAT-3)." (PMID 32466580, 2020). "Also, CD33+, STAT3+, and pSTAT3+ cells in BC tissue are significantly higher in the tumor tissues compared to the tumor margin and absent or low in healthy controls." (PMID 33679700, 2020). "Therefore, we analyzed the phosphorylation status of STAT3 in tumor tissue and cell culture and found that it did not change with the overexpression of RBP4." (PMID 32156052, 2020). "Intratumoral injection of STAT3 inhibitors also does not impede tumor growth, but it is surprising that the combination of sialiadase and STAT3 inhibitor JSI-124 can produce significant anti-tumor effects, which is related to the consumption of MDSCs at the tumor site." (PMID 33224886, 2020). "Our results indicate STAT3 signaling within CD103+ cDC1s elicits immunosuppressive responses including restrained expression of T cell co-stimulatory molecules and cytokines, as well as suppressed CD103+ cDC1-mediated increases in tumor antigen-specific CD8+ T cell and Th1 cell subsets in vivo." (PMID 31947933, 2020). "Therefore, it is obvious that a drug targeting the dimer and its Tyr705 phosphorylation would probably be ineffective if a tumor does not depend solely on the dimeric STAT3 and Tyr705 site for modification." (PMID 33371351, 2020). "However, the reduced induction of T-cell differentiation into Tregs and promoting effector Th cells, which generate interferon-γ (IFN-γ), can be implemented by blocking the signal transducer and activator of transcription 3 (STAT3) signaling pathway, thereby suppressing tumor growth." (PMID 32983126, 2020).